EGFR (epidermal growth factor receptor)
Diseases named in the same sentence as EGFR in open-access papers (continued):
Sharing a sentence is not in itself a finding about the gene and the disease.
breast carcinoma (continued). "Along with ESR-1; EGFR, MET, and VEGFR are located centrally in the network which indicates the role of proteins in the pathogenesis of breast cancer." (PMID 33057155, 2020). "Here we have shown that the TGFβ and EGFR pathways cooperate to activate an AP-1- and p63-dependent invasion program in various HER2+ and/or EGFR+ breast cancer cell lines." (PMID 32350443, 2020). "Hierarchical clustering of NCS‐1 and breast cancer molecular markers showed a positive correlation with basal and proliferative markers, such as KRT5, 14 and 17, CDH3, FOXC1, FOXM1, EGFR, and MKI67." (PMID 31647602, 2020). "In breast cancer cells, ANO1 promotes cancer progression by stimulating the cell proliferation signaling pathway involving EGFR and CaMKII." (PMID 32357567, 2020). "EGFR, also known as HER1, is also a member of the ErbB family receptor tyrosine kinase, and its overexpression of EGFR can be observed in breast cancer, head-and-neck cancer, non-small cell lung cancer, renal cancer, ovarian cancer, and colon cancer." (PMID 32560337, 2020). "Honeybee venom and melittin suppress the activation of EGFR and HER2 by interfering with the phosphorylation of these receptors in the plasma membrane of breast carcinoma cells." (PMID 32923684, 2020). "In contrast to KLF4, KLF8 induces invasion, proliferation, and metastasis in breast cancer, and in human breast cancers, KLF8 and EGFR are co-elevated." (PMID 32552913, 2020). "Williams et al83 identified a novel association between IKBKE and EGFR expression (P = .0011) using ICH (immunohistochemistry) analysis in breast cancer specimens, and knockdown of IKBKE using siRNA decreases the expression of EGFR." (PMID 31733040, 2020). "A breast cancer cell line (BT-20) and cervical cancer cells (HeLa) were selected due to distinctly different MET:EGFR expression levels." (PMID 32316583, 2020). "As a part of the present study, we determined that PGRMC1 specifically promotes breast cancer growth by activating the PI3K/AKT/mTOR and EGFR signalling pathway." (PMID 32704174, 2020). "NHERF1 suppressed EGFR phosphorylation and inhibited EGF-induced proliferation/migration in breast cancer cells." (PMID 32164629, 2020). "More specifically, SATB1 has been shown to be involved in the upregulation of EGFR (HER1), HER2, HER3, and HER4 in breast cancer cells." (PMID 33374770, 2020). "ELF5 is a transcription factor regulating key genes e.g., FOXA1, EGFR, and MYC, and has been described as potential regulator of anti-estrogen resistance in luminal breast cancer and imatinib resistance in chronic myeloid leukemia." (PMID 32429253, 2020). "Approximately 20% of breast cancers demonstrate amplification of the proto-oncogene HER2, a receptor tyrosine kinase (RTK) belonging to the epidermal growth factor receptor (EGFR) family, and approximately 30% of HER2-positive tumors show DM amplification." (PMID 33046109, 2020). "These two examples can clarify how CFIm25 interaction with distal region of EGFR and AKT3 3′-UTR mRNAs, can facilitates suppression of breast cancer tumorigenicity and metastasis, respectively." (PMID 32665581, 2020). "However, no reports exist as to any association between resistin and EGFR in breast cancer." (PMID 33313320, 2020). "In breast cancer, FABP5-PPARβ/δ functions downstream of EGFR signaling to promote tumor cell proliferation." (PMID 33352874, 2020). "In a multi-institutional cohort of 510 TNBC patients, we analyzed the impact of HER3, EGFR, or combined HER3-EGFR protein expression in pre-treatment samples on breast cancer-specific and distant metastasis-free survival (BCSS and DMFS, respectively)." (PMID 32080212, 2020). "These second-generation inhibitors irreversibly inhibit both EGFR and ErbB2 and have shown potency against HER2+ breast cancer." (PMID 32366937, 2020). "In breast cancer, EGFR silencing decreased NRG1 expression and invasion, while NRG1 silencing decreased EGFR expression and proliferation." (PMID 32552913, 2020).
breast carcinoma (continued). "Our previous researches implicate GPRC5A as a tumor suppressor in breast cancer cells, and GPRC5A exerts its tumor-suppressive function by inhibiting EGFR related cell proliferation." (PMID 33680947, 2020). "In preclinical models and early phase trials, combination of VEGF and EGFR inhibition has shown activity in advanced solid tumors, including CRC, NSCLC, breast cancer, renal cell carcinoma and HNSCC." (PMID 32337094, 2020). "In some solid tumors, such as gastric cancer, breast cancer, EMILIN2 can play essential functions in the tumor microenvironment, affecting tumor growth by directly binding epidermal growth factor receptor (EGFR) and lymphangiogenesis." (PMID 32175193, 2020). "In cancer research, Britschgi et al43 found ANO1 promoted breast cancer progression by CAMK and EGFR pathways." (PMID 32924329, 2020). "The overall pattern of CNAs in TNBCs resembled that generally observed in breast cancers, with the most frequent CNA events occurring at the level of PARK2 (6%), RB1 (5%), PTEN (3%), and EGFR (5%)." (PMID 32210163, 2020). "In breast cancer, these included VEGF signaling, EGFR signaling, and IGF1R signaling related pathways (all up-regulated in transcriptomics and down-regulated in proteomics)." (PMID 32907876, 2020). "Invasive tumor cells can migrate together with macrophages in primary mammary tumors in response to EGF and colony-stimulating factor 1 (CSF-1), which can be blocked by inhibiting either EGFR or CSF-1 signaling." (PMID 32883032, 2020). "Recently, it was reported that anti-EGFR protein-anchored PLGA-PEG NPs (immunonanoparticle, INP) for breast cancer therapy significantly enhanced tumor PTX concentrations by approximately 93-fold, compared to PLGA-PEG NPs and free PTX in athymic mice." (PMID 31197096, 2019). "Two additional dual HER2 and EGFR inhibitors, afatinib and neratinib, are undergoing clinical trials for treatment of BM from HER2-positive breast cancer with promising results." (PMID 31803366, 2019). "It was able to be delivered to breast cancer cells overexpressing HER-2 and the EGFR gene was efficiently downregulated in vitro, whilst a xenografted tumor growth was supressed in vivo." (PMID 31888119, 2019). "Totally, cantharidin inhibits multitarget proteins including EGFR, GLUT1, and PKM2 mediated glycolysis and MCTs, interfering the energy metabolism and finally leading to inhibition of breast cancer metastasis." (PMID 31178738, 2019). "In plasma membrane of breast cancer cells, 25 proteins get 27 N-glycosylation sites, such as BRCA-1, CD44, EGFR, can influence invasion and metastasis of breast cancer by regulating differentiation and proliferation of tumor cells." (PMID 31341840, 2019). "We found potential interactions between EGFR and PLC-γ activities, which have a role in breast cancer, whereby EGFR/human epidermal growth factor receptor 2/PLC-γ1 signaling results in tumor cell invasion and migration." (PMID 31285693, 2019). "In breast cancer, SHIP2 regulates epidermal growth factor receptor (EGFR) levels to support cell proliferation and tumor growth." (PMID 31357665, 2019). "In breast cancer xenografts, overexpressing EIF4E induces resistance to ERBB2 and EGFR inhibitors including lapatinib." (PMID 30072418, 2019). "To date, it has been found that ACK1 interacts with a variety of receptor tyrosine kinases (EGFR), oncoproteins (AKT), tumor suppressor proteins (Wwox), and epigenetic modification regulatory proteins (KDM3A) in breast cancer." (PMID 31772931, 2019). "Upon FIP200 depletion, they found a decrease in the phosphorylation of EGFR, with this resulting in decreased STAT3 activation and consequently in an impairment of ALDH+ breast cancer stem cells (BCSCs) tumorigenicity." (PMID 30728463, 2019). "Western blotting showed that EYA2 overexpression induced the up-regulation of YBX1, EGFR, cyclin E, and PCNA in both these two breast cancer cell lines." (PMID 30761270, 2019).
breast carcinoma (continued). "Many candidate genes emerged to be related to this breast cancer subtype, such as AKT1, AKT3, INPP4B, and EGFR." (PMID 30630526, 2019). "E2 activation of GPER leads to transactivation of the Epidermal Growth Factor Receptor (EGFR) and downstream activation of Mitogen-activated protein kinase (MAPK) and Phosphoinositide 3-kinase (PI3K) signaling cascades in breast cancer cells." (PMID 31212720, 2019). "Several clinical trials using rapalogs as combination therapy have been conducted in breast cancer, wherein HER2, a member of the epidermal growth factor receptor (EGFR), is often expressed or amplified." (PMID 31817676, 2019). "Similar results were obtained for HER+ breast cancer using a HER-2 sense and antisense bivalent aptamer conjugated to EGFR siRNA." (PMID 31888119, 2019). "Lapatinib, an orally administered small-molecule, is a dual tyrosine kinase inhibitor (TKI) that targets both HER-2 receptor and the epidermal growth factor receptor (EGFR), and which has been widely used for the treatment of breast cancer." (PMID 30987650, 2019). "This TKI also inhibits EGFR and Her4 and was approved in July 2017 by the FDA as an adjuvant to treat early stage Her2-positive breast cancer following trastuzumab therapy." (PMID 31756933, 2019). "Past work employed MDA-MB-468 TNBC cells and BT474 luminal B cells as models of EGFR and HER2-overexpressing breast cancer, respectively." (PMID 31839995, 2019). "Lapatinib is a dual receptor tyrosine kinase inhibitor (TKI) of epidermal growth factor receptor (EGFR) and ERB-B2 resceptor Tyrosine kinase (EEEB2) human epidermal growth factor receptor 2 (HER2), which is used for treating HER2-positive breast cancer." (PMID 30072418, 2019). "More recently, we discovered that disruption of the EGFR/ErbB2-dependent signalling by lapatinib and CP-724714, two inhibitors of the receptor tyrosine kinase (RTK), diminished the amplitude of the SOCE in breast cancer cells." (PMID 30917547, 2019). "BRCA_M14.n8 includes the hub gene SFRP1 as well as EGFR and FOXC1, PAM50 classifier genes used to define basal breast cancer (online)." (PMID 30993001, 2019). "AKT1 mediates this effect through a negative regulation of receptor tyrosine kinases like EGFR, whereas AKT2 is a suppressor of the pro-migratory miR-200 family like in breast cancer cells." (PMID 31752925, 2019). "As with HER2+ breast cancer, miR-205-5p can regulate TNBC growth by modulating members of the EGFR signaling pathway." (PMID 31752366, 2019). "Lapatinib inhibits the tyrosine kinases of HER2 and EGFR and is currently FDA approved for the treatment of breast cancer patients." (PMID 30975211, 2019). "Given these intriguing findings, the role of EGFR and downstream signaling pathways, such as PI3K/Akt and MAPK/Erk, in BPAF-mediated cellular responses in ER+ breast cancer cell models needs to be further examined." (PMID 31059536, 2019). "Cellular IF assay also showed that EYA2 overexpression enhanced the protein abundance of YBX1, EGFR, and PCNA in both breast cancer cell lines." (PMID 30761270, 2019). "Lapatinib, a reversible dual tyrosine kinase inhibitor of EGFR and HER2, has been approved for HER2-positive advanced breast cancer." (PMID 31569723, 2019). "cd-CAP also captured subnetworks relevant to the EGFR/ERBB2 signaling pathways, which have distinct expression patterns in specific subtypes of breast cancer." (PMID 30978274, 2019). "Lastly, an unexpected implication for NRF2 emerged from a recent work wherein the combined use of an HER2 inhibitor, Trastuzumab with an EGFR-inhibitor, Nimotuzumab, was assessed in the context of HER2-overexpressing breast cancer." (PMID 31097977, 2019). "In this article, we the silica nanoparticles (SLN) were surface conjugated with Cetuximab (Cet-SLN) to target epidermal growth factor receptor (EGFR), a common receptor that usually observed to overexpress in multiple breast cancers." (PMID 30798640, 2019).
breast carcinoma (continued). "Since S100A6 consistently demonstrated higher levels in all three lines we tested, we sought to determine the role of S100A6 in HER2-overexpressing breast cancer cells and in EGF/EGFR cell signaling through siRNA knockdown experiments." (PMID 30736768, 2019). "Approximately 25–30% of breast cancer patients highly overexpress HER2, and overexpression of EGFR and HER2 decreases disease-free survival and overall survival." (PMID 31569723, 2019). "In vitro, compared with mock-transduced NK-92 cells or primary NK cells, EGFR-CAR-engineered NK-92 cells and primary NK cells displayed enhanced cytotoxicity and IFN-γ production when co-cultured with breast cancer cell lines." (PMID 30805309, 2019). "Overexpression of miR-205-5p in breast cancer stem cells contributed to the development of trastuzumab resistance by lowering ERB2 and EGFR expression." (PMID 31752366, 2019). "We reported a novel EGF/EGFR axis that negatively fed back on the AJAP1-mediated β-catenin expression pathway and it accelerated breast cancer progression." (PMID 31171012, 2019). "In breast cancer cells, PTPH1 was shown to catalyze EGFR desphosphorylation of the phospho-tyrosine in pos." (PMID 30875834, 2019). "iEFs inhibited EGFR (Epidermal Growth Factor Receptor) activation, prevented formation of actin-rich filopodia, and hindered the motility of EGF-treated breast cancer cells." (PMID 31428691, 2019). "Binding of EGF and EGFR mainly activates the classical MAPK pathway and finally phosphorylates extracellular regulated protein kinase (ERK) to promote breast cancer cell proliferation." (PMID 30754684, 2019). "Similar to amphiregulin and TGF-α, EGF is reported to promote breast tumorigenesis through EGFR activation, and inhibition of EGF/EGFR signaling has been shown to exert anti-tumor effects for breast cancer." (PMID 31532771, 2019). "Numerous reports showed that overexpression of EGFR decreased OS and DFS in women with early breast cancer." (PMID 31171012, 2019). "For example, epidermal growth factor receptor (EGFR) and human epidermal growth factor receptor 2 (HER2) are overexpressed in colorectal cancer and breast cancer, respectively." (PMID 31387297, 2019). "Her2 is a member of the epidermal growth factor receptor (EGFR) family, commonly known as a tumor antigen over-expressed in 20 to 30% of breast cancers, but also expressed in many other cancer types." (PMID 31544819, 2019). "Taking advantage of this novel regulatory phenomenon, panitumumab, a humanized monoclonal antibody targeting EGFR, has been shown to significantly decrease the proliferation of ERBB2+ breast cancer." (PMID 31083325, 2019). "In breast cancer, co-immunoprecipitation and proximity ligation assay showed colocalization of EGFR and GD3, as well as EGFR activation by GD3 in cell membrane, avoiding the EGFR lysosomal degradation process." (PMID 31357634, 2019). "For breast cancer, a more interesting approach has been used to simultaneously target EGFR, HER2, and HER3 using a trivalent chimera made up from an EGFR siRNA positioned between two aptamers able to recognize, respectively, HER2 and HER3 (named H2EH3)." (PMID 31636244, 2019). "Real-time RT-PCR and Western blotting were used to examine EGFR RNA transcript and protein levels in the HS578T, MDA-MB-468, MDA-MB-231, and MCF-7 breast cancer cell lines." (PMID 31804974, 2019). "It is now clear through numerous studies that CTCs isolated from breast cancer patients express epithelial markers, receptors (ER, PR, HER2, EGFR), stem cell markers, and mesenchymal markers." (PMID 31261917, 2019).
breast carcinoma (continued). "Breast cancer subtypes can be characterised by the expression profiles of key signalling receptors (ERα, PgR, HER2 and EGFR)." (PMID 30987655, 2019). "Lapatinib (Tykerb) is a small-molecule inhibitor of kinase activity for both EGFR (HER-1) and HER-2 that has found use in breast cancer treatment in combination with chemotherapeutic agents and with the HER-2-directed monoclonal antibody drug trastuzumab." (PMID 30657766, 2019). "Lapatinib (LAP) is a dual kinase inhibitor of epidermal growth factor receptor (EGFR) and human epidermal receptor two (HER-2), which is widely used in HER-2-positive breast cancer." (PMID 30959904, 2019). "For example, MDM4 and EGFR were enriched in glioblastoma, MYC and ERBB2 were enriched in breast cancer whereas MDM2 was enriched in both." (PMID 30674876, 2019). "Generally, the experimental results evidenced that CAPE-pNO2 likely via inhibiting the EGFR/STAT3/Akt/E-cadherin signaling pathway to against growth and metastasis of breast cancer in vivo and in vitro." (PMID 31214503, 2019). "Among the most amplified genes, we find the oncogenes SOX2, EGFR, and MDM2, and also a noncoding gene, PVT1, the most amplified gene in breast cancer, with proven but as-of-yet uncharacterized proto-oncogenic effects." (PMID 31379928, 2019). "With this respect, Zhang and coworkers have focused on BT-474 and AU-565 breast cancer cells resistant to Lapatinib, a novel tyrosine kinase inhibitor of HER2/EGFR (epidermal growth factor receptor), used to treat HER2-positive breast cancer." (PMID 31097977, 2019). "Taking Lapatinib as an example, this drug is a dual inhibitor of EGFR and ERBB2 (or HER2), and was initially approved for treating breast cancer with over-expression of HER2." (PMID 30704449, 2019). "Altogether, our findings reveal an EGF signaling cascade involving EGFR, c-Src, and HDAC3 in breast cancer cells." (PMID 31430896, 2019). "Previous studies in breast cancer cells have identified FAM83A and B as interactors of different components within the EGFR pathway, like PI3K or RAF." (PMID 31083571, 2019). "In our cohort, all HER2 positive breast cancer patients had benefits from HER2 targeted therapy, and a higher expression of HER2, EGFR, PTEN and HER3 but lower expression of phospho-HER2 correlated with trastuzumab sensitivity." (PMID 30333908, 2018). "The high expression of CK5/6 and EGFR but low ER/PR and CK18 is compatible with basal-like breast cancer features." (PMID 29484537, 2018). "Therefore, the results obtained in this study indicate the main interactions that occur between the inhibitors studied and the biological targets and may help the proposition of new potential dual inhibitors of HER-2 and EGFR, candidates to treat breast cancer." (PMID 30477154, 2018). "In breast cancer, VPS37A was downregulated and inhibited breast cancer metastasis through downregulating EGFR phosphorylation." (PMID 29416742, 2018). "Although the relationship between EGFR/HER-2/ERK signaling and cisplatin resistance in breast cancer cells remains to be defined, the inhibition of the MAPK pathways sensitizes basal-like MDA-MB-468 cells to cisplatin treatment." (PMID 29940998, 2018). "Compared with that of the untreated control groups, the EGFR knockdown significantly inhibited the TGF‐β‐induced enhancement of the migration and invasion abilities of two breast cancer cells." (PMID 29215776, 2018). "This suggests that HER2/EGFR and other RTK signaling pathways are aberrantly activated in non-HER2 amplified breast cancers." (PMID 29590203, 2018). "IGF1R, EGFR, AXL, VEGFR are other RTK members share common downstream signaling molecules such as PI3K/Akt/mTOR and MAPK with HER2 in breast cancer." (PMID 29455658, 2018).